LINC00957 (long independently transcribed non-coding RNA 957)
Gene: Long non-coding RNA gene on chromosome 7 (44,039,049 to 44,044,375, forward strand). Ensembl gene ENSG00000235314.
Diseases named in the same sentence as LINC00957 in open-access papers:
LINC00957 is named in the same sentence as 5 diseases in open-access papers, as found by Europe PMC text mining. Sharing a sentence is not in itself a finding about the gene and the disease. The quoted sentences say what the papers report.
colorectal cancer (3 papers, 2019 to 2024). A primary or metastatic malignant neoplasm that affects the colon or rectum. "LINC00957 has also been reported to be upregulated in colorectal cancer cell lines, especially in 5-Fu-resistant cell lines; however, silencing ofLINC00957 via siRNA can significantly reverse 5-Fu resistance in 5-Fu-resistant cell lines." (PMID 39439418, 2024).
Colon Cancer (2 papers, 2019 to 2022). "A total of 709 autophagy-related genes were identified in colon cancer tissues, and 11 autophagy-related lncRNAs (AL138756.1, LINC01063, CD27-AS1, LINC00957, EIF3J-DT, LINC02474, SNHG16, AC105219.1, AC068580.3, LINC02381, and LINC01011) were finally selected and set as prognosis-related lncRNAs." (PMID 36035142, 2022).
tumor (2 papers, 2019 to 2023). "Aberrant expression of LINC00957 was associated with CRC in GTEx dataset, and his upregulation was confirmed by qRT-PCR in patients' tumor and paired normal tissues." (PMID 31497531, 2019).
cancer (1 paper, 2022). A tumor composed of atypical neoplastic, often pleomorphic cells that invade other tissues. "Among the 11 autophagy-related lncRNAs, 8 lncRNAs were already verified to be associated with cancer development: LINC01063, CD27-AS1, LINC00957, EIF3J-DT, LINC02474, SNHG16, LINC02381, and LINC01011." (PMID 36035142, 2022).
LINC00957 also shares sentences with these, for which no sentence is quoted: fibroids (2 papers).